HK2 (hexokinase 2)
Diseases named in the same sentence as HK2 in open-access papers (continued):
Sharing a sentence is not in itself a finding about the gene and the disease.
allergic asthma (1 paper, 2024). A asthma with a basis in a pathological type I hypersensitivity reaction. "Additionally, the glycolysis inhibitor 3-BP (HK2 inhibitor) antagonized S100A9 overexpression, effects, suggesting that the regulation of glycolysis plays a critical role in the involvement of S100A9 in allergic asthma and HK2 might be a target of S100A9." (PMID 38646478, 2024).
amyloid (1 paper, 2025). "Additionally, in an AD mouse model, pharmacological inhibition of hexokinase 2 (HK2), a key glycolytic enzyme, increased LPL expression, which in turn regulated lipid metabolism and was associated with reduced amyloid load and improved cognitive function." (PMID 40149001, 2025).
anemia (1 paper, 2025). A reduction in the number of red blood cells, the amount of hemoglobin, and/or the volume of packed red blood cells. "Angelica sinensis polysaccharides facilitate the expression of the glycolytic gene Hk2, which promoted splenic glycolysis and extramedullary stress erythropoiesis, thereby ameliorating anemia." (PMID 40574855, 2025).
aneurysm (1 paper, 2023). Bulging or ballooning in an area of an artery secondary to arterial wall weakening. "Although the number of VSMCs in the aneurysm wall was reduced and the alignment was disordered, the expression of SPARC was increased and the expression of HK2 was significantly reduced compared to normal vascular tissue." (PMID 38076208, 2023).
Aortic dissection (1 paper, 2025). Aortic dissection refers to a tear in the intimal layer of the aorta causing a separation between the intima and the medial layers of the aorta. "Therefore, the role of HK2 in aortic dissection warrants further investigation." (PMID 40342964, 2025).
asthma (1 paper, 2025). "Airway epithelium is a key structural component in the pathogenic process of asthma, yet the expression and functional role of HK2 in airway epithelial cells remain unexplored in asthma." (PMID 40643524, 2025). "This may restrict the ability to fully evaluate the association between HK2 expression and specific asthma phenotypes or endotypes." (PMID 40643524, 2025). "Our findings demonstrate that HK2, a key enzyme in glycolysis, is overexpressed in the airway epithelium of asthma patients and mouse asthma models." (PMID 40643524, 2025). "Given the observed elevation of HK2 expression in both asthma patients and murine models, we developed a mouse model with airway epithelium-specific HK2 deficiency to explore its role in asthma pathogenesis." (PMID 40643524, 2025). "Immunohistochemical analysis of airway biopsies from seven asthma patients and eight healthy controls confirmed a significant elevation in HK2 expression within the airway epithelial cells of asthma patients." (PMID 40643524, 2025). "Our sequencing analysis and experiments findings confirmed that elevated HK2 promotes epithelial apoptosis in asthma." (PMID 40643524, 2025). "Unlike classical type 2 inflammatory cytokines, which did not alter HK2 expression, IL-1β signaling played a pivotal role in HK2 upregulation in asthma." (PMID 40643524, 2025). "Given global HK2 deletion is embryonically lethal, we generate Hk2 flox/flox Scgb1a1-iCre+/- mice to explore how HK2 functions in asthma." (PMID 40643524, 2025). "This study aimed to investigate metabolic alterations in asthma, focusing on the expression, function and regulation of HK2." (PMID 40643524, 2025). "In the present study, we observed significantly elevated HK2 expression in the airway epithelium of asthma patients, suggesting that HK2 participates in asthma pathogenesis by contributing to airway epithelial cell apoptosis and inflammation." (PMID 40643524, 2025). "Consistently, HK2 expression was elevated in both asthma individuals and mice with allergic airway inflammation." (PMID 40643524, 2025). "To further investigate the function of HK2 in asthma, we generated Hk2flox/flox-Scgb1a1-iCre+/- mice, in which HK2 was specifically deleted in club cells." (PMID 40643524, 2025). "Furthermore, treatment with 2-DG significantly ameliorated airway inflammation and AHR, supporting the involvement of HK2 in asthma pathogenesis." (PMID 40643524, 2025). "Moreover, pharmacological inhibition of HK2 with 2-DG significantly improved AHR and pulmonary inflammation in asthmatic mice, identifying HK2 as a promising therapeutic target for managing asthma." (PMID 40643524, 2025). "However, the roles of hexokinase 2 (HK2) in asthma remain incompletely understood." (PMID 40643524, 2025). "Additionally, the HK2 inhibitor 2-DG was utilized to further validate the effects of HK2 in asthma." (PMID 40643524, 2025). "Elevated HK2 expression in airway epithelial cells regulates glycolysis, airway inflammation, and apoptosis, thereby contributing to airway inflammation and AHR in asthma." (PMID 40643524, 2025). "Although these findings support a functional link between HK2 and PPIF in regulating epithelial apoptosis, the precise integration of this pathway with other known regulators of epithelial cell death and airway inflammation in asthma remains unclear." (PMID 40643524, 2025). "Furthermore, given the heterogeneity of asthma endotypes, including type 2 and non-type 2 inflammation, it is plausible that the HK2-PPIF axis may differentially contribute to epithelial dysfunction across distinct asthma subtypes." (PMID 40643524, 2025).
bone tumor (1 paper, 2022). "We report a blood-based CTC test of OS, a mesenchymal bone tumor, that uses HK2 as a marker for detecting CTCs according to their metabolic abnormalities." (PMID 36172793, 2022).
cataract (1 paper, 2023). Partial or complete opacity of the crystalline lens of one or both eyes that decreases visual acuity and eventually results in blindness. "Thus, whether HK2 is involved in cataracts requires further exploration." (PMID 37414399, 2023).
co-infection (1 paper, 2023). "Here, using a model of viral-bacterial co-infection in the airways, we demonstrate that the antiviral IFN response promotes secondary P. aeruginosa infection through the upregulation of the ISG HK2, which is required for the WE and apical L-lactate secretion." (PMID 37939149, 2023).
coronary atherosclerosis (1 paper, 2020). Atherosclerosis of the coronary vasculature. "In patients with severe symptomatic coronary atherosclerosis, monocytes display a distinct glycolytic phenotype by overexpressing hexokinase 2 and PFKFB3." (PMID 33282864, 2020).
cutaneous melanoma (1 paper, 2025). A primary melanoma arising from atypical melanocytes in the skin. "In addition, in patients with cutaneous melanoma, HK2 expression was significantly higher in stages III–IV compared to stages I–II (p = 0.026)." (PMID 40956859, 2025).
Dengue virus infection (1 paper, 2023). "Increased expression of GLUT1 and HK2 was also observed during Dengue virus infection." (PMID 37259080, 2023).
Desminopathy (1 paper, 2016). "So we analyze bax, bcl2,bcl-xl, and HK2 expression and location in the muscle fibersof patients with desminopathy by using immunofluorescences." (PMID 27941998, 2016). "Meanwhile apoptosis related proteins bax and ATF2 were involved in desminopathy patients and desminopathy rat model, but not bcl-2, bcl-xl or HK2.VDAC1 and desmin are closely relevant in the tissue splices of deminopathies patients and rats with desminopathy at protein lever." (PMID 27941998, 2016). "Moreover, apoptotic proteins are also involved in the desminopathies, like bax, ATF2, but not bcl-2, bcl-xl or HK2." (PMID 27941998, 2016).
diabetic foot ulcers (1 paper, 2024). "Finally, we identified retinoic acid and estradiol as promising anti-diabetic foot ulcers by targeting hexokinase-2 (−6.6 and −7.2 kcal/mol), small ribosomal subunit protein us3 (−7.5 and −8.3 kcal/mol), and l-lactate dehydrogenase A chain (−7.6 and −8.5 kcal/mol)." (PMID 39044840, 2024).
diffuse gastric adenocarcinoma (1 paper, 2026). An adenocarcinoma arising from the stomach. "Background/Objectives: To evaluate the immunohistochemical expression of hexokinase-2 (HK2), glutaminase-1 (GLS1), and fatty acid synthase (FASN) and its prognostic significance in diffuse gastric adenocarcinoma." (PMID 41892863, 2026).
dilated cardiomyopathy (1 paper, 2020). Cardiomyopathy which is characterized by dilation and contractile dysfunction of the left and right ventricles. "Overexpression of miR-143 and miR-145 leads to a unique dilated cardiomyopathy phenotype with a reductive redox shift despite marked downregulation of HK2 expression." (PMID 32855642, 2020).
epithelial dysplasia (1 paper, 2018). "The ventral prostate (VP) and dorsal-lateral prostate (DLP) lobes have higher hK2 expression and a greater incidence of epithelial dysplasia and carcinoma compared to the anterior prostate (AP) lobes, and as a consequence demonstrated a greater uptake of [225Ac]hu11B6." (PMID 29691406, 2018).
esophageal tumor (1 paper, 2017). "Thus, our finding of a HK2-glucose link in hyperplastic ZD esophagus highlights the critical role of HK2 in deregulated glucose metabolism in early esophageal tumor development by ZD." (PMID 29137232, 2017).
fibrosarcoma (1 paper, 2022). A malignant mesenchymal fibroblastic neoplasm affecting the soft tissue and bone. "Through anion exchange and siRNA adsorption, the resulting multifunctional siRNA@ABMBP-COF, which possesses both the HK2 inhibitor 3-bromopyruvate and SLC7A11 siRNA, exhibits powerful synergistic antitumor activity against fibrosarcoma via the ferroptosis and apoptosis pathways." (PMID 35865896, 2022).
follicular lymphoma (1 paper, 2015). Follicular lymphoma is a form of non-Hodgkin lymphoma characterized by a proliferation of B cells whose nodular structure of follicular architecture is preserved. "The other genes, such as HK2, CENPF, CTPS, LDHA, P2RY5 and DNASE1L3 also can be identified in both transformation follicular lymphoma and ‘indolent’ type FL." (PMID 26416427, 2015).
gastric tumors (1 paper, 2021). "Subsequently to the higher intracellular glucose levels, Hexokinase 2 (HK-2), the first enzyme of the glycolytic pathway, is consistently overexpressed in gastric tumors and is associated with poor survival in patients with digestive system malignancies." (PMID 34249759, 2021).
gestational diabetes (1 paper, 2025). Carbohydrate intolerance first diagnosed during pregnancy. "Subsequent research will delve into the effects of reducing CCNB1 on additional essential metabolic controllers like AMPK, HK2, and FASN, in order to gain a more comprehensive understanding of its broader involvement in metabolic control during gestational diabetes." (PMID 39822992, 2025).
glaucoma (1 paper, 2013). Increased pressure in the eyeball due to obstruction of the outflow of aqueous humor. "So the HK2 gene may contribute to disease susceptibility to POAG and NTG, but may not account for all of the phenotypic variability between individuals whose glaucoma results from variants in this gene." (PMID 23349798, 2013). "This localization makes it highly conceivable that the Hk2 gene products could each play a role in glaucoma, and there is possibility that Nck2 could have relationship with glaucoma." (PMID 23349798, 2013).
Granuloma (1 paper, 2021). A compact, organized collection of mature mononuclear phagocytes, which may be but is not necessarily accompanied by accessory features such as necrosis. "The bacterial colony forming units (CFUs) and granulomas were reduced in rMPT-treated mice; however this difference was not significant in mice lacking TBK1, p47phox, or HK2, compared to the control." (PMID 34068051, 2021).
HCMV infection (1 paper, 2022). "Interestingly, non-TNFα treated HK2 KO and HIF1A KO cells showed an increase in HCMV plaque formation relative to the vehicle pretreated control ntg cells, suggesting that HIF1A and HK2 may play a role in restricting HCMV infection that is independent of TNFα signaling." (PMID 35834576, 2022).
hemorrhage (1 paper, 2026). Loss of blood from the vascular compartment to the exterior or into nonvascular body space as a result of rupture or severance of the blood vessels. "Particularly, Hk2 and Tnf demonstrated the most pronounced spatial enrichment around the hemorrhage site, with consistent high expression patterns observed across consecutive timepoints, indicating coordinated spatial regulation of these genes in response to hemorrhagic injury." (PMID 41601478, 2026).
hemorrhagic stroke (1 paper, 2026). A stroke caused by a bleed on the brain. "These contrasting responses across hemorrhagic models highlight a common pattern of HK2 regulation characterized by an initial decline followed by a later rise, with day 7 representing a critical transition point in the metabolic and inflammatory evolution of hemorrhagic stroke." (PMID 41601478, 2026).
hepatitis B virus infection (1 paper, 2025). A viral infection caused by the hepatitis B virus. "Hepatitis B virus infection induces the formation of a ternary complex that includes hexokinase 2 (HK2), which blocks the retinoic acid-inducible gene-1 (RIG-1) like receptor (RLR) signaling pathway, thereby facilitating viral immune evasion." (PMID 40552816, 2025).
hepatoblastoma (1 paper, 2024). Hepatoblastoma (HB) is a malignant hepatic tumor and is the most common pediatric liver cancer. "Key molecular drivers of the Warburg effect in hepatoblastoma include Hypoxia-Inducible Factor 1-α (HIF-1α), which, stabilized by hypoxia or Wnt/β-catenin signaling, promotes glycolysis by upregulating enzymes like hexokinase 2 (HK2), phosphofructokinase (PFK1), and pyruvate kinase M2 (PKM2)." (PMID 39596558, 2024).
hepatocellular adenoma (1 paper, 2021). A benign epithelial neoplasm arising from the hepatocytes. "In hepatocellular adenoma (HCA) and a subset of HCC, the expression and activity of PPARG is significantly increased, affecting metabolic rearrangements and liver tumorigenesis via the transcriptional regulation of hexokinase 2 (HK2) and M2 pyruvate kinase (PKM2)." (PMID 34771521, 2021).
idiopathic pulmonary fibrosis (1 paper, 2022). Idiopathic pulmonary fibrosis (IPF) is a nonneoplastic pulmonary disease that is characterized by the formation of scar tissue within the lungs in the absence of any known cause. "In the lung tissue of patients with idiopathic pulmonary fibrosis (IPF), disruption of amino acid metabolism and glycolysis has been evidenced and glycolytic enzymes (including PFKFB3, PFK1, and HK2) are upregulated." (PMID 36121543, 2022).
keratitis (1 paper, 2025). A corneal disease that is characterized by inflammation of the cornea. "Having established the antiviral effects of HK2 inhibition in vitro, we extended our findings to an in vivo model to evaluate the therapeutic potential of targeting HK2 within the setting of HSV‐1‐induced keratitis." (PMID 40539869, 2025).
kidney damage (1 paper, 2025). "Overall, targeting HK2 or GLUT1 could serve as a promising therapeutic strategy for LN by regulating macrophage metabolism to reduce kidney damage." (PMID 41161814, 2025).
kidney inflammation (1 paper, 2025). "By enhancing glycolysis, HK2 and GLUT1 provide metabolic support for the proinflammatory M1-type macrophages, thus exacerbating kidney inflammation." (PMID 41161814, 2025).
kidney injury (1 paper, 2023). Trauma to the kidney. "Thus, it is demonstrated that HK2 deficiency-mediated mitophagy inhibition is the critical mechanism in HIF-1α CTAD knockout-induced kidney injury." (PMID 37225700, 2023).
leukoplakia (1 paper, 2018). A white patch or plaque on a mucous membrane that cannot be characterized clinically or pathologically as any other disease. "Similarly, Sal-B treatment inhibited GLUT1 and HK2 expression in OSCC cells and premalignant leukoplakia cells." (PMID 29789538, 2018).
liposarcoma (1 paper, 2012). A usually painless malignant tumor that arises from adipose tissue. "This is in agreement with a study of miR-143 in liposarcoma that also did not identify ERK5 as a miR-143 target, but did observe a down-regulation of HK2 in response to miR-143 overexpression." (PMID 22691140, 2012).
lupus nephritis (1 paper, 2020). Glomerulonephritis in the context of systemic lupus erythematosus. "There was a significant positive correlation between Hk2 and Hif1a and Il1b transcripts in MRL-lpr kidneys with lupus nephritis, implicating HIF1α-induced glycolysis in the induction of autoantibody-mediated inflammation in vivo." (PMID 32541026, 2020).
Lyme borreliosis (1 paper, 2021). "Indeed, increased PFKFB3, HK2, and LDHA gene expression has been observed in Lyme borreliosis patients, as well as increased levels of serum lactate." (PMID 33395408, 2021).
metabolic syndrome (1 paper, 2022). A cluster of metabolic risk factors for CARDIOVASCULAR DISEASES and TYPE 2 DIABETES MELLITUS. "In terms of metabolism, it has been found that targeting NR4A1 can regulate glycolytic key enzymes GLUT4, HK2, and PFK in the liver and muscle cells to target metabolic syndromes." (PMID 36052242, 2022).
metastatic cancer (1 paper, 2023). A carcinoma which has spread from the original site of growth to another anatomic site. "In the content of the lactate biosynthesis pathways, over-expression of hexokinase 2 (HK2) and lactate dehydrogenase A (LDHA), the committed steps to regulate magnitude and direction of glucose flux for lactate production, are required for tumor initiation, maintenance, and metastatic cancer spread." (PMID 36986244, 2023).
migraine (1 paper, 2023). "Compared with CON group, quantitative real-time polymerase chain reaction showed that PFKP (2.02 ± 0.51), HK2 (2.55 ± 0.72), HIF-1α (3.05 ± 0.61) and PKM2 (1.97 ± 0.49) mRNA expression increased in migraine model group." (PMID 37090989, 2023). "In the experimental model of migraine, key enzymes involved in glycolysis such as phosphofructokinase platelet (PFKP), hexokinase (HK2), hypoxia inducible factor-1α (HIF-1α), lactate dehydrogenase (LDH) and pyruvate kinase (PKM2) were expressed in the medullary dorsal horn." (PMID 37090989, 2023). "To explore whether glycolysis increased during the experimental models of migraine, we detected the gene expression of important enzymes related to glycolysis, such as PFKP, HK2, HIF-1α, LDH and PKM2." (PMID 37090989, 2023).
monoclonal gammopathy of undetermined significance (1 paper, 2020). "We found that the level of HK2 expression in active MM disease was significantly higher than that in normal plasma cells (NPCs) and premalignant cells, including monoclonal gammopathy of undetermined significance (MGUS) and smoldering MM (SMM)." (PMID 32709889, 2020).
mucinous carcinoma (1 paper, 2021). "In addition, GLUT1, HK2, PFKP, PGK1, and PKM2 had higher expression levels in mucinous carcinoma." (PMID 34277429, 2021).
Optic neuropathy (1 paper, 2024). "Given the importance of HK2-encoding proteins in mitochondria, it is reasonable to believe that the variant phenotypes could induce metabolic dysfunction and, furthermore, optic neuropathy." (PMID 38674425, 2024).
ovarian serous cystadenocarcinoma (1 paper, 2022). A malignant serous cystic epithelial neoplasm arising from the ovary. "The positive correlation between HK2 and CDH2, fibronectin, MMP9, ZEB1, ZEB2 and vimentin in OV (ovarian serous cystadenocarcinoma) was confirmed by using TIMER 2.0." (PMID 35953860, 2022).
parasitosis (1 paper, 2016). "Having experienced these rare cases, we investigated the mechanisms of FDG uptake in parasitosis lesions by immunohistochemical staining using antibodies to glucose transporter type 1 (GLUT-1) and hexokinase type 2 (HK-2)." (PMID 27112922, 2016).
periodontal disease (1 paper, 2023). "Therefore, HK2-mediated glycolysis may be a potential target for the host-modulated treatment of periodontal disease in the future, through the topical use of HK2 inhibitors." (PMID 36793034, 2023).